TAP1 (transporter 1, ATP binding cassette subfamily B member)
Diseases named in the same sentence as TAP1 in open-access papers (continued):
Sharing a sentence is not in itself a finding about the gene and the disease.
cancer (continued). "Among them, TAP1 was identified as a reliable prognostic target for pan-cancer immunotherapeutic response, which increases PDL1 expression and can be enhanced by oxaliplatin stimulation." (PMID 40108724, 2025). "Targeting NLRC5 promoter demethylation through TRED-I system can upregulate MHC-I, B2M, TAP1 and genes encoding immune proteasome components (LMP2/PSMB9/β1i, LMP7/PSMB8/β5i), thereby enhancing CD8+T cell-mediated anti-cancer immunity." (PMID 40191187, 2025). "Consistent with our results, previous studies have also shown that the alterations in TAP1 and TAP2 proteins in cancer cells are uncommonly associated with deleterious genomic alterations and were suggested to occur as a consequence of protein dysregulation." (PMID 40091029, 2025). "We then confirmed the downregulation of TAP1/2 expression in Map3k1-mut cancer cells compared with Map3k1-WT cancer cells in the coculture system by quantitative PCR with reverse transcription (RT–qPCR) analysis and Western blot assay." (PMID 39531335, 2024). "Next, we investigated the genetic alteration status of TAP1 in TCGA pan-cancer cohort, including the types and frequencies of genetic alterations." (PMID 36759763, 2023). "Spearman correlation analysis of the relationship between TAP1 expression and infiltration levels of multiple immune cell lineages in the pan-cancer cohort was conducted." (PMID 36759763, 2023). "Spearman’s correlation analysis was conducted to evaluate the correlations between TAP1 expression and levels of individual ICPs across TCGA pan-cancer types." (PMID 36759763, 2023). "Based on these data, we propose TAP1 as a novel biomarker for predicting patient prognosis and the effects of immunotherapy in diverse cancers." (PMID 36759763, 2023). "In this study, we performed a comprehensive pan-cancer analysis to generate a TAP1 expression landscape across various cancer types." (PMID 36759763, 2023). "Although the present study provides rigorous evidence demonstrating the predictive role of TAP1 in clinical prognosis and potential responses to immunotherapy across pan-cancer, it has limitations." (PMID 36759763, 2023). "Pan-cancer correlations between TAP1 expression and immunotherapy biomarkers were explored using the Spearman’s correlation test." (PMID 36759763, 2023). "Our results revealed a highly concentrated distribution of enrichment across 33 pan-cancer types, where immune-related pathways were strongly enriched for in cancers with high TAP1 high expression." (PMID 36759763, 2023). "Our results revealed aberrant expression of TAP1 in the majority of pan-cancer types, and that this expression is significantly correlated with clinical prognosis, immune cell infiltration, expression of ICPs, TME biomarkers, and immunotherapy efficacy." (PMID 36759763, 2023). "Combining currently available results, we conclude that TAP1 expression is highly correlated with immune regulation, and corresponds to a distinct immune signature for each pan-cancer type." (PMID 36759763, 2023). "Using GSEA, we evaluated TAP1 enrichment in hallmarks gene sets, and found prominent enrichment in immune-related pathways, which was consistent across pan-cancer cohorts." (PMID 36759763, 2023). "In our study, 47 ICPs were tested for their correlation with TAP1 mRNA expression across a pan-cancer dataset." (PMID 36759763, 2023). "Focusing on copy number variation in pan-cancer types, TAP1 expression was significantly correlated with copy number variation in KICH and kidney renal papillary cell carcinoma (KIRP)." (PMID 36759763, 2023). "To further explore the potential value of TAP1 for prognosis prediction, we next analyzed the prognostic role of TAP1 across cancers." (PMID 36759763, 2023). "In this study, we conducted multi-omics research to explore the roles of TAP1 in prognostic prediction, immune cell infiltration, hallmarks associated with the TME, and prediction of immunotherapeutic responses on a pan-cancer scale." (PMID 36759763, 2023).
cancer (continued). "Such novel treatments have inspired investigations of clinical prognosis and informed selection of optimal treatments based on the specific cancer types involved and individual transcriptome patterns of biomarkers, such as TAP1." (PMID 36759763, 2023). "Heatmap analysis indicated that TAP1 expression was positively correlated with most ICPs in the majority of pan-cancer types, particularly BRCA, KIRC, PRAD, TGCT, THCA, and UVM." (PMID 36759763, 2023). "Studies on TAP1 have continuously emerged over recent years, with novel findings in several cancers." (PMID 36759763, 2023). "Further, positive correlations were mainly concentrated in the same cell lineages; that is, specific infiltrated cell types were positively correlated with TAP1 expression in numerous cancer types." (PMID 36759763, 2023). "To evaluate the prognostic implications of TAP1 expression, we used Kaplan–Meier and univariate Cox regression models to assess its clinical translational potential in each cancer type." (PMID 36759763, 2023). "This is distinguished to previous studies in many cancers, which, however, are mainly focused on the low expression of TAP1 in the early stage of tumorigenesis, suggesting the relation of low expression of TAP1 to the high level of DNA methylation." (PMID 36419887, 2022). "ScRNA-seq also demonstrated that CRC cells treated with FTD have a lower expression of HLA-I molecules, B2M, and TAP1, all involved in antigen presentation and commonly downregulated in cancers as a mechanism of immune escape." (PMID 35831404, 2022). "The loss of expression of MHC class I and TAP1 allow some cancer cells to evade immune surveillance and contribute to the clinical course of OSCC and other cancers." (PMID 35454851, 2022). "The results showed that TUBA1C had a positive correlation with most MHC-related genes in THCA, BLCA, and BRCA, and the TAP1 gene was positively correlated with TUBA1C in almost all cancer types, suggesting that TAP1 is a potential immunotherapeutic target." (PMID 36466547, 2022). "The NPS was significantly and positively associated with HLA genes, including TAP1, HLA-E, HLA-DRA, B2M, TAP2, HLA-DPA1, and HLA-DOA in all cancers." (PMID 36170029, 2022). "An oncoprint plot showed genomic alterations in genes encoding the HLA-I, B2M, TAP1 and TAP2 that would influence antigen presentation, amounting to ~12% of 10,967 cancer patients in the TCGA data set." (PMID 36612246, 2022). "A previous study proposed TAP1 to be adopted as cancer treatment via immunotherapy considering its importance in the peptide MHC-I complex and as the role of elevating the immune response." (PMID 36419887, 2022). "In particular, the TAP1 gene was positively correlated with TUBA1C in almost all cancer types, indicating that TAP1 can serve as a promising immunotherapy target." (PMID 36466547, 2022). "Some glycosylation enzymes (GALNT7, GCNT1, TAP1, PGM3, etc.)are under the control of AR and link to the synthesis of cancer-associated glycans such as sialyl-Tn (sTn), sialyl LewisX (SleX)." (PMID 35853851, 2022). "This subpopulation shows overexpression of TP53I3 and TAP1 correlated to multidrug resistance in human cancers and with the presence of hypoxic conditions." (PMID 34109737, 2022). "Analysis in the databases revealed the mutation in TAP1, frequency alteration and copy number alterations of the gene and the pathways of correlated genes, which can be further studied to understand the mechanisms of TAP1 gene in cancer cells." (PMID 34047812, 2021). "We explored the expression of TAP1 protein derived from antibody-based protein profiling using immunochemistry for the different cancer tissues and their counterpart normal tissues." (PMID 34047812, 2021). "Both TAP1 and APOD are closely related to antitumor immunity, and studies have shown that TAP1 plays an important role in a variety of cancers." (PMID 34247148, 2021).
cancer (continued). "We saw an upregulation of TAP1 mRNA not only in various cancers, but also, in primary tumors, different stages, ethnicities, and gender, when compared with normal tissues of BRCA, LIHC, and LUAD." (PMID 34047812, 2021). "Hence, TAP1 mutation may be used as a target for immunotherapy in cancer patients." (PMID 34631788, 2021). "It provided us with data regarding the quantitative difference between normal and cancer cells, where all the cancers showed a noticeable fold change in the TAP1 expression." (PMID 34047812, 2021). "To analyze the mRNA expression for the TAP1 gene in different kinds of cancer, we used three databases." (PMID 34047812, 2021). "Generated database queried to observe the genetic mutation of TAP1 in 7710 specimens from 12 cases of BRCA, LIHC, LUAD and OV cancers." (PMID 34047812, 2021). "The study found the relationship between the TAP1 expression pattern and prognosis in different cancer tissues and shows how TAP1 affects the clinical characteristics." (PMID 34047812, 2021). "Statistically significant overexpression of the TAP1 gene in cancer patients from different ethnicity compared to normal tissues were seen in BRCA, LIHC, and LUAD." (PMID 34047812, 2021). "We used the bioinformatics methods to determine the function of TAP1 in predicting the prognosis, immune infiltration, and immune checkpoint genes in various cancers." (PMID 34957213, 2021). "To explore the ability of TAP1 in predicting the prognosis of various cancers, we used the KM analysis to calculate the relationship between TAP1 expression and survival status in 33 tumors using the patient information in the TCGA." (PMID 34957213, 2021). "We wanted to do a systematic inquiry of the computational data to see if TAP1 affected the survival rate of patients with various cancers." (PMID 34047812, 2021). "To verify the trend we analyzed the expression of TAP1 protein levels in normal and cancer tissues of breast, liver, lung and ovaries by using the Human Protein Atlas project database." (PMID 34047812, 2021). "Overall, we did find significant increase of TAP1 expression in cancer tissues in several databases, which indicates a relationship between TAP1 expression and multiple cancers." (PMID 34047812, 2021). "To understand the role of TAP1 expression in different cancers, we used ONCOMINE, GEPIA2, and GENT2 databases." (PMID 34047812, 2021). "By analyzing the correlation between TAP1 and methyltransferases in pan-cancers, we found that TAP1 had a significant correlation with the 4 methyltransferases in KICH and DLBC." (PMID 34957213, 2021). "The GEPIA2 server was then used to study the profile of TAP1 expression levels in multiple cancer types through ANOVA testing with an adjusted p-value of 0.05." (PMID 34047812, 2021). "We analyzed the relationship between TAP1 and neoantigens across various cancers as summarized by Rooney." (PMID 34957213, 2021). "We used ONCOMINE to look into the comparison of TAP1 mRNA expression for different cancer and their normal tissues." (PMID 34047812, 2021). "Overall, the study provided a new aspect to consider the role of TAP1 gene in cancer progression and survival status." (PMID 34047812, 2021). "Even though, the TAP1 levels for different cancer stages showed fluctuating levels of TAP1 but the analysis showed significantly elevated TAP1 for BRCA, LIHC, and LUAD for all stages compared to the normal tissues." (PMID 34047812, 2021). "Giving us an expression that with an increased level of TAP1, there is a weaker probability of survival for the mentioned cancers." (PMID 34047812, 2021). "TAP1 influences multidrug resistance (MDR) in human cancer cell lines and hinders the treatment during chemotherapeutic." (PMID 34047812, 2021). "The network surrounding Il10ra shows that many of them are cancer related, e.g., Reg3g, Aoc1, Mep1a, Irf7, Gas6, B3gnt7, Tap1, Tgm2, and Nos2." (PMID 33396408, 2020).
cancer (continued). "Many investigations in the literature have demonstrated loss of TAP1 and TAP2 expression in human cancers." (PMID 29091951, 2017). "Previous studies demonstrated that the TAP1 gene, which participates in antigen processing, has a CpG island and is frequently methylated in cancer." (PMID 26883197, 2016). "The level of acetyl-histone H3 strongly correlated with the level of TAP1 expression and with metastatic features in malignant carcinomas." (PMID 25699047, 2015). "There was a different expression pattern among cancer cell lines for HLA class I heavy chain (HLA-HC), β2 microglobulin, Tapasin, TAP-1, TAP-2, LMP-7 and LMP-10." (PMID 22134332, 2012). "Prognostic factors were the down-regulation of HLA-HC, and the up-regulation of β2 microglobulin and TAP-1 in the cancer tissues." (PMID 22134332, 2012). "Multivariate analysis using a Cox regression model indicated that the down-regulation of HLA-HC, and up-regulation of TAP-1 in cancer tissues are independent, unfavorable prognostic factors (hazard ratio, 2.361 and 2.297; P=0.0141 and 0.0145, respectively)." (PMID 22134332, 2012). "Together, these results suggest that TAP2 downregulation in cancer cells could be more energy-efficient and produce a deeper immune evasion than TAP1 reduction." (PMID 40091029, 2025). "Hence, we propose TAP1 as a novel biomarker that can predict prognosis and immunotherapeutic responses in different cancer types, opening a new chapter in the exploration of TAP1 in malignancies." (PMID 36759763, 2023). "TAP1 expression was elevated in most cancer types and exhibited distinct prognostic value." (PMID 36759763, 2023). "To determine whether TAP1 protein levels were also aberrantly expressed in cancer samples, we conducted western blot assays to verify the results of informatics analysis of RNA-seq data." (PMID 36759763, 2023). "The transporter associated with antigen processing (TAP) plays a critical role in peptide delivery, and cancer cells can modulate TAP1 and/or TAP2 levels to reduce peptide delivery, thereby evading recognition by cytotoxic CD8+ T cells (El Hage, Durgeau & Mami-Chouaib, 2013)." (PMID 37483962, 2023). "Overall, aberrant expression TAP1 mRNA levels were detected in various cancer types." (PMID 36759763, 2023). "Our results indicate that TAP1 is a powerful and promising biomarker for predicting cancer prognosis and could benefit patients receiving immune therapy." (PMID 36759763, 2023). "As concluded based on the findings of prognostic and ICP correlation analyses, TAP1 expression correlation varied among cancer types, which may be related to differences in the predictive role of TAP1." (PMID 36759763, 2023). "Cancer types showing significant correlations between TAP1 expression and patient outcomes may benefit from TAP1-targeted treatment, which could be advantageous to populations sensitive to such regimens." (PMID 36759763, 2023). "TAP1 regulates normal immune responses, and is abnormally expressed in various cancer types; therefore, we hypothesized that it is a potential biomarker for predicting immunotherapeutic efficacy." (PMID 36759763, 2023). "Thus, we propose TAP1 as a promising and powerful biomarker to predict the effects of immunotherapy in patients with cancer." (PMID 36759763, 2023). "Further, we report basic information regarding TAP1 in pan-cancer cohorts and explore the relationship between TAP1 expression and prognosis, enriched gene sets, immune cell infiltration, expression of immune regulators, and immunotherapeutic effects on a pan-cancer scale." (PMID 36759763, 2023). "Therefore, due to the different genetic backgrounds, the overall effect of TAP1 in different cancer species is varying." (PMID 36419887, 2022). "And the increased expression of TAP1 resulted in more immune cells infiltrated in cancer tissues." (PMID 36419887, 2022). "We, here, gather computational integrative omics data analysis for TAP1 in multiple cancers." (PMID 34047812, 2021).
cancer (continued). "We also wondered if TAP1 expression in different cancers were different, i.e. if certain cancers would have higher TAP1 result and another cancer kind will have a lower TAP1 expression hence, the analysis of expression in multiple cancers would help us be clearer on that aspect." (PMID 34047812, 2021). "Our results showed that TAP1 could play an important role in immunotherapy across various cancers, and we determined the expression of TAP1 in cell lines and tissues to explain its role in the prognosis of CC and OC." (PMID 34957213, 2021). "The boxplot showed tissue wide expression of TAP1 among cancer experiments." (PMID 34047812, 2021). "We investigated BRCA, LIHC, LUAD and OV cancers patients’ prognosis related to the TAP1 expression." (PMID 34047812, 2021). "• An upregulation of TAP1 mRNA was demonstrated in various cancer types." (PMID 34047812, 2021). "We need analytical data to show the standpoint of TAP1 in various cancers." (PMID 34047812, 2021). "It gave us more clarity as TAP1 protein levels were elevated for all four kinds of cancer." (PMID 34047812, 2021). "Thus, our results indicated further studies should be performed to establish the role of TAP1 as a prognostic marker in many cancers." (PMID 34957213, 2021). "Interestingly, our results showed that TAP1 expressions were seen to be higher in cancer tissues in some cancers." (PMID 34047812, 2021). "Consequently, it generated the expression of TAP1 mRNA (RNA Seq V2) among 12 cases of cancers by utilizing the cBioPortal." (PMID 34047812, 2021). "Furthermore, we wanted to see if a patient with cancer had any clinical characteristics related to the TAP1 gene and how it varies in different cancers." (PMID 34047812, 2021). "We further investigated the TAP1 gene expression pattern in various cancer kinds." (PMID 34047812, 2021). "By utilizing the cBioPortal database, genetic alteration of TAP1 in different cancers were studied." (PMID 34047812, 2021). "Particularly, TAP1 is an important HLA class-I surface peptide, and recent works have shown that impairement of this epigenetically regulated gene is responsible of the escape of cancer cells from the host’s immuno-surveillance." (PMID 30718669, 2019). "When treated with 5-AC, 6/8 of the cancer lines showed a significant upregulation of TAP1." (PMID 28622390, 2017). "And we further speculated that the high expression of TAP1 could be one of cancer stem cell-like cells features." (PMID 28402962, 2017). "Thus, TAP1 is a potentially promising and powerful prognostic biomarker for various cancers." (PMID 36759763, 2023). "Thus, our results showed that TAP1 could function as a biomarker for cancer diagnosis and prognosis." (PMID 34957213, 2021). "The downregulation of ß2-m,TAP1, TAP2, LMP7, ERAP1, tapasin, and ERp57 protein expression positively associated with HLA-I expression in CIN lesions, whereas ß2-m, TAP1, TAP2, LMP2, LMP7, ERAP1, ERp57, and tapasin expression positively associated with HLA-I in the cancerous lesions." (PMID 23024775, 2012). "High SLC7A11 levels in NPC cells led to reduced MHC-I antigen presentation by limiting TAP1 transcription and activating ERAD-dependent MHC-I degradation, which can hinder the recognition of cancer cells by the immune system." (PMID 39820491, 2025). "In BC tissues, TAP1, PILRA, UBE2C, TMEM51, and MKI67 were significantly upregulated, while the expression levels of SPP1 and CENPF remained unchanged between cancer and adjacent tissues." (PMID 41328437, 2025). "TAP1, critical for MHC class I antigen processing and display, exhibits elevated expression across multiple cancer types and holds significant prognostic value." (PMID 40108724, 2025). "Meanwhile, in most cancer types, a noteworthy positive connection was observed between ESRRA and TAP1 (belonging to MHC) and TNFRSF14." (PMID 40356747, 2025).